CRP (C-reactive protein)
Diseases named in the same sentence as CRP in open-access papers (continued):
Sharing a sentence is not in itself a finding about the gene and the disease.
appendicitis (continued). "In a meta-analysis examining the accuracy of CRP levels in the diagnosis of acute appendicitis, a wide range of sensitivity (40 – 99%) and specificity (27 - 90%) was found in literature." (PMID 24693387, 2013). "CRP, leukocyte count were significantly higher in the acute appendicitis group, and RDW level were significantly lower in the acute appendicitis group (p < 0.001, p < 0.001, p = 0.001, respectively)." (PMID 24216220, 2013). "Similar to the literature, this study found a sensitivity of 97% and a specificity of 41% for CRP in the diagnosis of acute appendicitis." (PMID 24216220, 2013). "The median CRP level was 15.26 ± 58.55 mg/dL in the acute appendicitis group and 2.6 ± 5.09 mg/dL in the control group." (PMID 24693387, 2013). "A recent meta-analysis showed that when both an elevated WBC count and elevated C-reactive protein level are present, there is a fivefold increase in the positive likelihood ratio for acute appendicitis." (PMID 22447205, 2012). "In those with positive appendicitis, the CRP and WBC values were elevated in 126 patients (72.8%), whereas NP was higher than 75% in 117 patients (67.6%)." (PMID 22866907, 2012). "We recommend CRP measurement as a routine laboratory test in patients with suspected diagnosis of acute appendicitis." (PMID 22866907, 2012). "In our study, the CRP values corresponds to the series with high percentage of complicated appendicitis, which is typical for rural hospitals and dysfunctional healthcare systems." (PMID 22866907, 2012). "Grönroos (1999) in his study concluded that when both the WBC and CRP are normal, acute appendicitis is very unlikely." (PMID 22866907, 2012). "This score incorporated the C-reactive protein value in its design and was developed and validated on a prospective cohort of patients with suspicion of acute appendicitis." (PMID 22447205, 2012). "Our results and other studies as well, clearly suggested that CRP leads to precise prediction of the severity of acute appendicitis." (PMID 22866907, 2012). "Many reports have investigated the value of the raised serum CRP measurement in improving the diagnosis of acute appendicitis." (PMID 22866907, 2012). "Combining all three parameters (WBC, CRP and percentage of neutrophil count) had positive results for the appendicitis in 101 (68.24%) patients (Groups B and C), and only 5 patients had one or more values in the normal range." (PMID 22866907, 2012). "The combination of the CRP, the WBC, and the neutrophil percentage has greater diagnostic accuracy in acute appendicitis." (PMID 22866907, 2012). "Hs-CRP concentration in acute suppurative is significantly higher than that of acute simple, and Hs-CRP of acute gangrenous appendicitis patients is remarkably higher than acute suppurative group (P < 0.01)." (PMID 22947457, 2012). "But, the consistence of CRP level with the severity of appendicitis was reported by the other authors as well." (PMID 22866907, 2012). "In our study, from 148 patients with acute appendicitis, 22 patients had CRP and WBC in the normal range (12.72%)." (PMID 22866907, 2012). "In this background, CRP and white blood cell counts are important for the diagnosis for appendicitis." (PMID 19878592, 2009). "This study is an attempt to clarify the role of C-reactive protein (CRP) as a surgical indication marker for appendicitis." (PMID 19878592, 2009). "Some reports indicated that appendicitis is unlikely, when the white blood cells count and CRP value are normal." (PMID 19878592, 2009). "The current study clearly suggested that CRP leads to precise prediction of the severity of acute appendicitis for treatment." (PMID 19878592, 2009). "If CRP can be added to the already existing laboratory tests, the diagnosis of acute appendicitis with clinically suggestive signs can be made with a fair degree of accuracy and, as such, unnecessary appendectomies can be avoided." (PMID 19568576, 2009).
appendicitis (continued). "Only the CRP level is consistent with the severity of appendicitis, and considered to be a surgical indication marker for acute appendicitis." (PMID 19878592, 2009). "The logistic regression analysis indicated that only the CRP level is an independent marker for distinguishing the severity of acute appendicitis." (PMID 19878592, 2009). "The sensitivity and specificity of TLC, CRP and percentage of neutrophil in the diagnosis of acute appendicitis was calculated individually and in combination." (PMID 19568576, 2009). "The TLC was found to be significantly high in 90 patients who proved to have acute appendicitis, whereas CRP was high in only 88 patients and neutrophil percentage was raised in 91; four had a normal CRP level." (PMID 19568576, 2009). "Multivariate analysis indicated only the CRP level to be a surgical indication marker for acute appendicitis." (PMID 19878592, 2009). "The CRP level, which is a commonly used clinical tool, has been clearly demonstrated to contribute to the prediction of the severity of appendicitis." (PMID 19878592, 2009). "The receiver-operating characteristic (ROC) curve indicated that the cutoff value of CRP for surgical indication of appendicitis is 4.95 mg/dl." (PMID 19878592, 2009). "Another prospective study has shown that it is important to measure serial CRP levels and white blood cell counts in patients with suspected appendicitis." (PMID 19878592, 2009). "Scores of studies have been conducted to determine the role of TLC and CRP in the diagnosis of acute appendicitis, with all giving varying results." (PMID 19568576, 2009). "The sensitivity of CRP levels in predicting appendicitis was 60% on admission and increased to 100% by the fourth blood specimen." (PMID 19878592, 2009). "If clinical symptoms and image examinations indicate that a patient has appendicitis, a patient with a high CRP level should undergo surgery immediately." (PMID 19878592, 2009). "It has been shown, that WBC count, serum CRP, and IL-6 are helpful tools to support the clinical diagnosis of phlegmonous and perforated appendicitis in childhood." (PMID 17132173, 2006). "In a metaanalysis CRP has been shown to have a medium sensitivity (53–88 %) and specificy (46–82 %) for appendicitis." (PMID 17132173, 2006). "In contrast, in patients with markedly elevated inflammatory markers (CRP > 100), 39.0% of respondents would operate during the night based on clinical suspicion of acute appendicitis, rising to 48.8% if the diagnosis had been confirmed with pre-operative imaging." (PMID 41507411, 2026). "Furthermore, salivary CRP levels showed an excellent ability to differentiate children with acute appendicitis from controls (AUC = 0.97; 95% CI 0.91–0.99; p < 0.001)." (PMID 40871545, 2025). "CRP is thus not only influenced by the cellular immune system, but also by other cells in the body, which could make it a helpful tool for diagnosing acute appendicitis in immunocompromised patients." (PMID 40596935, 2025). "Studies have described in detail that elevated CRP levels may correspond to further complications of appendicitis, e.g., perforation or abscess." (PMID 41153524, 2025). "Furthermore, CRP levels showed a substantial increase in appendicitis patients (median: 32.90 mg/L vs. 1.12 mg/L, p < 0.001), consistent with acute inflammation." (PMID 40804906, 2025). "The clinical picture often mimics that of classical acute appendicitis, but inflammatory markers such as leukocyte count and C-reactive protein (CRP) may remain within normal limits." (PMID 41209983, 2025). "Since acute appendicitis triggers an acute inflammation, related inflammatory markers include C-reactive protein (CRP), procalcitonin (PCT, ng/mL), erythrocyte sedimentation rate, interleukin-6, systemic immune-inflammation index (SII) and systemic inflammatory response index." (PMID 41251102, 2025).
appendicitis (continued). "In this particular study, the analysis of laboratory markers from our two pediatric surgery centers identified hyponatremia as a more significant marker of complicated appendicitis compared to more commonly used laboratory parameters such as C-reactive protein (CRP) and neutrophil count." (PMID 40506956, 2025). "These patients were included in the cohort and may partly explain the higher rate of non-appendicitis cases, lower CRP values and lower frequency of surgical intervention." (PMID 40948509, 2025). "While CRP is an established marker for the diagnosis and prognosis of acute pancreatitis and diverticulitis, it possesses only a limited accuracy for diagnosing appendicitis." (PMID 39159989, 2025). "C-reactive protein (CRP) also remains a plausible target, correlating with appendicitis severity." (PMID 41153524, 2025). "In addition, CRP is also regularly elevated in a variety of diseases, making it difficult to differentiate appendicitis from other diseases in children." (PMID 41153524, 2025). "With suspected appendicitis at a CRP threshold of 52.5 mg/L, at least PHL could be expected (49% sensitivity, 95% specificity, AUC 0.72)." (PMID 40825891, 2025). "Mann-Whitney U test demonstrated significant differences in the WCC, neutrophil, lymphocyte and eosinophil count, NLR, NER, and CRP between patients demonstrating acute appendicitis on histopathology versus those with normal appendiceal tissue or E. vermicularis." (PMID 41523465, 2025). "Notably, PCT has been found to have both higher sensitivity (97%) and specificity (80%) for diagnosing appendicitis than CRP (95% and 74%, respectively)." (PMID 41153524, 2025). "CRP, another commonly used marker, was not measured in this study but has been frequently associated with inflammation in appendicitis, particularly in combination with WBC." (PMID 39764342, 2025). "A CRP cut-off of ≥3.95 was effective in predicting acute appendicitis on histopathology." (PMID 41523465, 2025). "Studies have demonstrated that elevated WBC and CRP can differentiate patients with appendicitis from those without, although these markers lack specificity for distinguishing between simple and complex cases of appendicitis." (PMID 39764342, 2025). "While CRP is a non-specific inflammatory marker, its diagnostic utility in appendicitis lies in its integration with clinical signs, scoring systems, and imaging." (PMID 40871545, 2025). "Several studies have explored the utility of biochemical markers in the diagnosis and risk stratification of acute appendicitis - certainly in the adult population, white cell (WCC) and neutrophil count, as well as C-reactive protein (CRP), have shown variable performance as a diagnostic tool." (PMID 41523465, 2025). "More importantly, in a subgroup analysis based on the proximity of the medical center to conflict zones, we found that the rate of complicated appendicitis doubled during the war only in medical centers close to conflict zones, along with a trend toward increased CRP levels in this population." (PMID 40648989, 2025). "Compared to the control group, patients in the appendicitis group showed statistically significantly higher white blood cell, neutrophil, C-reactive protein, immature granulocyte count, immature granulocyte percentage, and neutrophil-to-lymphocyte ratio levels (p<0.001 for all)." (PMID 40531775, 2025). "Our hypothesis is that combining MAS with serum CRP measurements will be better at predicting appendicitis than MAS alone." (PMID 39677268, 2024). "A pre- matching comparison showed that the SILA group was younger (p < 0.01), had lower preoperative inflammatory response (p = 0.04 for WBC, p < 0.01 for CRP), had fewer prior surgeries (p = 0.01), and was less likely to have perforated appendicitis or intraperitoneal abscess formation (p < 0.01)." (PMID 39840002, 2024). "Inflammatory markers, like CRP, may also be elevated in ovarian torsion and other common pathologies, i.e., appendicitis and TOA." (PMID 39252715, 2024).
appendicitis (continued). "Therefore, we aim to examine the correlation between CRP levels at hospital admission and the duration of hospitalization in pediatric patients with appendicitis who underwent laparoscopic appendectomy." (PMID 39726534, 2024). "The probability that an individual who has positive CRP/MAS indeed has acute appendicitis." (PMID 39677268, 2024). "Furthermore, research has demonstrated that CRP levels can aid in the identification of complicated appendicitis, with particularly elevated levels observed in cases of perforated appendicitis." (PMID 39726534, 2024). "A combination of WCC >11 × 109/L, neutrophil count >7× 109/L, evidence of left shift (>75% neutrophils:lymphocytes) and a CRP >5 mg/L was significant for a diagnosis of appendicitis (P < 0.001) with a specificity of 88% for the diagnosis of AA, with a positive predictive value of 80%." (PMID 39139307, 2024). "When comparing patients with complicated appendicitis who were correctly identified at ED by the doctor to patients wrongfully classified as having uncomplicated appendicitis, these previously published distinctive variables (age and CRP level) differ significantly." (PMID 38228896, 2024). "Hematological parameters such as total leucocyte count (TLC), neutrophil count, NLR, PLR, and CRP were significantly higher in patients with complicated appendicitis on operative findings, whereas these patients also had lower preoperative hemoglobin and plasma sodium (Na) levels (p < 0.05)." (PMID 39624500, 2024). "In the multivariate analysis ASA Score of 3, elevated WCC, high CRP, presence of gangrenous or perforated appendicitis, peritonitis, and microbiologic testing were independent predictors of prolonged antibiotics, where age and intraoperative finding of an abscess were not." (PMID 38062298, 2024). "However, an increase in neutrophil percentage to ≥85.30% and a rise in C-reactive protein to ≥34.26 mg/L in the third trimester strongly suggest the presence of complicated appendicitis." (PMID 38953065, 2024). "In conclusion, this study demonstrated a non-linear association and threshold effect between CRP and length of stay in pediatric patients with appendicitis who underwent laparoscopic appendectomy." (PMID 39726534, 2024). "This association may be attributed to the inflammatory nature of NLR and CRP, which typically increase as appendicitis progresses." (PMID 39735250, 2024). "This relationship may be attributed to CRP as a marker for the inflammatory response, with elevated levels reflecting the severity of appendicitis and the degree of infection-related inflammation." (PMID 39726534, 2024). "Furthermore, various studies have suggested that when WBCs and CRP values are within the normal range, the likelihood of acute appendicitis is low, and it is generally safe to discharge the patient." (PMID 37251740, 2023). "This high value is also attributable to the fact that they included complicated appendicitis in their study as well, and most of those patients had a higher mean CRP level, which could’ve skewed the values obtained by them." (PMID 38024038, 2023). "Using the multivariate analysis, C-reactive protein level, maximal outer diameter of the appendix, and presence of appendiceal fecalith were identified as independent predictors for developing gangrenous/perforated appendicitis." (PMID 37286951, 2023). "However, the serum CRP concentration was significantly elevated in patients with gangrenous/perforated appendicitis as compared to those with phlegmonous appendicitis (Kruskal-Wallis test; P < .01)." (PMID 36691230, 2023). "However, the mean CRP level and the likelihood of intraperitoneal culture post-rupture were significantly higher in those with complicated appendicitis." (PMID 37303416, 2023).
appendicitis (continued). "Although the Dutch GP guideline does not support using CRP, due to a lack of evidence that it adds value above symptoms and signs of appendicitis among children in primary care, a recent study of registration data has shown that a CRP test result does add value in this setting." (PMID 37872491, 2023). "Similarly, a triad of CRP >60 g/L, WCC >12 × 109/L, and age >60 years are associated with complicated appendicitis." (PMID 37143626, 2023). "When the CRP values of the pregnant women undergoing appendectomies were compared according to the pathology results, the mean CRP value of the patients with appendicitis was 7.80 ± 10.19 mg/L, while the mean CRP value of the patients without appendicitis was 2.27 ± 3.21 mg/L." (PMID 37115072, 2023). "Albumin, CRP, lymphocytes count, neutrophils count, WBC count, CRP/Albumin ratio, CRP/MPV ratio, albumin/MPV ratio and neutrophils/lymphocytes ratio were found to be directly or inversely associated with severity of appendicitis." (PMID 36707812, 2023). "Similarly, the erythrocyte sedimentation rate (ESR), c-reactive protein (CRP), white blood cell count, neutrophil-lymphocyte ratio, and platelet-lymphocyte ratio were also significantly raised in patients with acute appendicitis." (PMID 37685553, 2023). "C-reactive protein (CRP) level, white blood cell (WBC) count, erythrocyte sedimentation rate (ESR), and body temperature also showed important associations with complicated appendicitis." (PMID 36900066, 2023). "Obviously, CRP may exhibit a delay to rise of up to12 h after the onset of symptoms of appendicitis in children, andmay have a delayed peak of up to 48 h, thus lags behind TLC, consequently, it may be less reliable at the time of referral." (PMID 37862106, 2023). "Moreover, CRP levels are precise predictors of appendicitis severity, especially when interpreted with the respective white blood cell and neutrophil counts." (PMID 37303416, 2023). "In order to establish the diagnosis of acute appendicitis, most of the surgeons will ask for a complete blood count, C reactive protein and an abdominal ultrasound, and 69.5% of surgeons responded that they rarely use a CT or an MRI in the diagnosis of acute appendicitis in pediatric patients." (PMID 36556939, 2022). "Both groups were matched one for one according to gender, duration of symptoms, c-reactive protein at presentation and whether they presented with uncomplicated or complicated appendicitis." (PMID 36358179, 2022). "The best single test for ruling in appendicitis was a CRP value ≥50 mg/L and so could be the most useful in deciding to rule in the diagnosis of appendicitis." (PMID 36328382, 2022). "CRP was observed in our study to be an independent marker of severity in acute appendicitis." (PMID 35495380, 2022). "However, if CRP levels 12 h after the onset of symptoms are <2.5 mg/dL, acute appendicitis can be excluded." (PMID 35495380, 2022). "We found no other study looking at the diagnostic value of CRP for appendicitis in children with abdominal pain in primary care." (PMID 35535699, 2022). "While they share no other organ system involvement, which could just be mild and remain untested, they do appear clinically like complicated acute appendicitis cases with high CRP values." (PMID 36013568, 2022). "Diagnostic scores for appendicitis include special emphasis on patient history, physical examination findings, and laboratory results (such as white blood cell count [WCC] and/or C-reactive protein [CRP])." (PMID 36237793, 2022). "Several authors have studied some possible predictive factors (C-reactive protein, leukocytosis, duration of symptoms, presence of fever) of complicated appendicitis to evaluate the urgency of the surgical approach, in order to help distinguish the severity of this pathology." (PMID 35106154, 2022).